ICAM1 (intercellular adhesion molecule 1)
Diseases named in the same sentence as ICAM1 in open-access papers (continued):
Sharing a sentence is not in itself a finding about the gene and the disease.
Hypertension (continued). "In addition, targeted inhibition of ICAM1 might be an effective treatment for hypertension, because ICAM1 knockdown could inhibit Ang II‐induced arterial hypertension and vascular hypertrophy." (PMID 40329406, 2025). "In addition to chemokines, ICAM-1 also plays an important role in hypertension development." (PMID 35222039, 2022). "Moreover, VCAM-1 but not ICAM-1 also associates with LVM in patients with uncomplicated essential hypertension, and in patients with hypertensive concentric LVH." (PMID 26398099, 2015). "Dendrobium also decreases hypertension via activating PI3K/AKT/eNOS signaling pathways, NO generation, and inhibition of ICAM-1 and ET-1." (PMID 37396948, 2023). "Monocyte recruitment is the key factor in the development of vascular inflammation, followed by adhesion molecules (VCAM-1 and ICAM-1), inflammatory factors (TNF-α and IL-6), and chemokines (CCL2, CXCL5, CXCL8, and CXCL10) released during hypertension." (PMID 34335249, 2021). "IL-1β in essential hypertension enhances VCAM-1, ICAM-1, and E-selectin expression with atherosclerotic effects." (PMID 31186952, 2019). "Studies have shown that adhesion molecules ICAM-1, VCAM-1, immune cells, chemokine CCL2, and CXCR3 are key factors in human hypertension; these series of events results in the progression of hypertension." (PMID 29573749, 2018). "Our results demonstrate that activation of PPAR-α attenuates Ang II-induced hypertension through up-regulation of CYP4A and CYP2J and an attenuation of inflammatory markers such as plasma IL-6, renal MCP-1, renal expression of ICAM-1 and COX-2." (PMID 22848208, 2012). "Gene expression of ICAM-1, VCAM-1 and RANTES was unaltered whereas Osteopontin and MCP-1 were induced by hypertension." (PMID 15918915, 2005). "The pooled results showed that the mean value of ICAM-1 (ng/mL) was significantly higher in the hypertension group, where MD: 85.28 95%CI: (50.57–119.99); there was no significant heterogeneity between the studies, where I2 = 11%." (PMID 40217768, 2025). "Moreover, atorvastatin has a beneficial impact on endothelial function and inflammation, which is reflected by decreased serum levels of ICAM-1 and TNF-α levels in hypertension." (PMID 37759223, 2023). "Other hypotheses suggest that activin A involvement in preeclampsia pathogenesis rely on endothelin-1, ICAM-1 and VCAM-1 overexpression, favouring hypertension and oedema." (PMID 37595293, 2023). "Ang II infusion upregulates ICAM-1 expression, promoting LFA-1+ macrophage adhesion to the endothelium and leading to the production of multiple proinflammatory cytokines and ROS, resulting in hypertension." (PMID 35222039, 2022). "In patients with untreated stage I hypertension, daily consumption of 100 g dark chocolate for 15 days did not affect ICAM-1 and CRP." (PMID 27240397, 2016). "Further research need to focus on more inflammatory biomarkers such as intercellular adhesion molecule-1 (ICAM-1), endothelin-1, and others as well as their pathways to understand the possible molecular mechanisms involved in the inducing of hypertension by heated palm oil." (PMID 22778962, 2012). "Arterial hypertension affected the values of s-Endocan, s-VCAM-1 and s-E-Selectin, but did not influence s-ICAM-1 concentration." (PMID 39862311, 2025). "The present study therefore investigated the effect of a single-pill combination of amlodipine and atorvastatin calcium on the circulating levels of ICAM-1 and TNF-α in patients with hypertension with or without prediabetes." (PMID 27610083, 2016). "Accordingly, it has previously been shown that levels of inflammatory regulators intracellular adhesion molecule (ICAM-1) and vascular cell adhesion molecule (VCAM-1) were upregulated immediately after the CPT in people with and without hypertension, compared to resting levels." (PMID 40597238, 2025).
ischemic stroke (76 papers, 2011 to 2026). A stroke disorder caused by obstruction of blood flow to the brain, due to thrombotic (local blood clot formation) or embolic (due to a blood clot or other material traveling from another site) event. "Elevated baseline serum levels of soluble intercellular adhesion molecule-1 (sICAM-1), an inflammatory marker, were independently associated with a more than twofold increased risk of future ischemic stroke in patients with chronic coronary heart disease." (PMID 40949500, 2025). "In the present meta‐analysis, we investigated the association between K469E polymorphism of ICAM‐1 gene and risk of ischemic stroke." (PMID 31157518, 2019). "In all three genetic models, subgroup analysis showed that K469E polymorphism of ICAM‐1 gene was associated with ischemic stroke in the Caucasians population." (PMID 31157518, 2019). "Despite these limitations, our meta‐analysis indicated that Caucasians with the ICAM‐1 gene K469E polymorphism are susceptible to ischemic stroke." (PMID 31157518, 2019). "Evidence suggests that K469E polymorphism of ICAM‐1 is a risk factor for ischemic stroke susceptibility among Caucasians." (PMID 31157518, 2019). "In this study, we conducted extensive review of the literature and conducted a meta‐analysis to assess the relationship between the ICAM‐1 gene K469E polymorphism and susceptibility to ischemic stroke." (PMID 31157518, 2019). "In the current meta‐analysis, we investigated the relationship between the ICAM‐1 gene K469E SNP and the risk of ischemic stroke." (PMID 31157518, 2019). "In addition, in humans, genetically elevated higher soluble ICAM-1 and E-selectin levels were found to be associated with poor prognosis following ischemic stroke." (PMID 40949500, 2025). "Moreover, the rs5498 polymorphism of ICAM-1 has been associated with an increased risk of ischemic stroke in Caucasian populations." (PMID 40066310, 2025). "In addition, a recent meta-analysis showed that the rs5498 polymorphism of ICAM-1 is associated with a higher risk of ischemic stroke in Caucasian subjects." (PMID 36745280, 2023). "However, in all three genetic models, subgroup analysis revealed that the K469E polymorphism of the ICAM‐1 gene is associated with ischemic stroke in the Caucasian population." (PMID 31157518, 2019). "In addition to the K469E polymorphism of the ICAM‐1 gene, a study has shown that the ICAM‐1 gene G1548A polymorphism is an independent risk factor for the development of ischemic stroke (Lu, Liu, Wu, Chen, & Hwang, 2013)." (PMID 31157518, 2019). "K469E polymorphism of ICAM‐1 gene might be a risk factor for ischemic stroke in Caucasians, which suggested that K469E polymorphism might help in early identification of those at risk and help in primary prevention of ischemic stroke." (PMID 31157518, 2019). "Considering the importance of ICAM‐1 pathogenesis of ischemic stroke, further larger studies with gene–environment interactions in diverse ethnicity should be conducted to clarify the association between K469E polymorphism and ischemic stroke susceptibility." (PMID 31157518, 2019). "In addition, soluble ICAM‐1 levels are also associated with neurological deterioration following ischemic stroke." (PMID 31157518, 2019). "Of the 20 studies included, only 6 were Caucasian studies, which may have affected the true association of Caucasian ICAM‐1 polymorphism with ischemic stroke." (PMID 31157518, 2019). "The endothelial adhesion molecules VCAM-1 and ICAM-1 have been associated with transendothelial diapedesis of leukocytes and subsequent secondary neuroinflammation in various non-inflammatory CNS disorders and particularly experimental ischemic stroke." (PMID 21967730, 2011).
ischemic stroke (continued). "Interestingly, phospholipid-rich EMP levels were found to be higher in patients with acute stroke, and EMP carrying ICAM-1 have been found to correlate with stroke lesion volume and functional outcome, underlining their potential role as prognostic biomarkers in ischemic stroke management." (PMID 40949500, 2025). "This identifies the NF-κB/NLRP3-VCAM1/ICAM-1 pathway as a potential therapeutic target for preventing recurrent cardiac vascular events post-ischemic stroke." (PMID 41798606, 2026). "In the acute phase of ischemic stroke, the proliferation of venous ECs increased, with high ICAM‐1 expression, promoting the infiltration of myeloid cells." (PMID 40421577, 2025). "Overall, the diagnostic and prognostic value of ICAM-1 and VCAM-1 in ischemic stroke remains incompletely understood, necessitating further research and clinical validation." (PMID 40066310, 2025). "Studies have reported changes in ECs following ischemic stroke, particularly the upregulation of adhesion molecules such as ICAM‐1 and VCAM‐1." (PMID 40421577, 2025). "Our analysis indicated that ICAM1 vascular expression at the lesion site remained unchanged 1 week after ischemic stroke upon increasing PDGF-D subacute bioavailability." (PMID 38769116, 2024). "An elevated expression of ICAM-1 was also confirmed within hours after the onset of ischemic stroke, at 6 and 72 h after hemorrhage and in examined hippocampal CA1 regions." (PMID 36979834, 2023). "Of much interest, ICAM has been the target of a randomized clinical trial in which patients with ischemic stroke received an anti-ICAM-1 antibody, enlimomab." (PMID 36745280, 2023). "After ischemic stroke, it induces ICAM-1 and increases the expression of MMPs, promoting blood–brain barrier (BBB) disruption." (PMID 37762627, 2023). "Our results have revealed that ischemic stroke results in upregulated expression of adhesion molecules (P‐selectin, E‐selectin, and ICAM‐1) and chemokines (CCL‐2, CCL‐3, CCL‐4, CCL‐5, and CXCL‐1)." (PMID 37122157, 2023). "In summary, ischemic stroke results in upregulated expression of adhesion molecules (P‐selectin, E‐selectin, and ICAM‐1) and chemokines (CCL‐2, CCL‐3, CCL‐4, CCL‐5, and CXCL‐1)." (PMID 37122157, 2023). "For instance, Deddens and co-workers performed molecular MRI of intercellular adhesion molecule-1 (ICAM-1) in an experimental model of ischemic stroke in mice." (PMID 34065179, 2021). "We investigated serum concentrations of E-selectin, VEGF-A, VCAM-1, and ICAM-1 in healthy controls and ischemic stroke patients within 8 h of symptom presentation and again at 72 h." (PMID 32595585, 2020). "ICAM1 protein expression levels were also quantified by immunoblotting at 1, 4, 7, and 14 days post ischemic stroke." (PMID 31043599, 2019). "An inhibition of Icam1 had protective effects after ischemic stroke as previously reported in a rat model." (PMID 29896414, 2018). "For example, apelin significantly reduces the expression of inflammatory cytokines in rat brains, such as interleukin 1 beta (IL-1β), TNF-α and intercellular adhesion molecule 1(ICAM-1), and inhibits cell apoptosis in rats with ischemic stroke." (PMID 28167898, 2017). "ICAM-1 expressed on ECs facilitates neutrophil adhesion and tissue infiltration, which play critical roles in the progress of ischemic stroke." (PMID 25315906, 2014). "We concluded that metformin conferred resistance to ischemic stroke through decreasing ICAM-1 via the AMPK signaling pathway." (PMID 25315906, 2014). "Since ICAM-1 plays a vital role in neutrophil infiltration and cerebral injury after reperfusion, it is a promising target in the treatment of ischemic stroke." (PMID 25315906, 2014). "Therapies targeting ICAM-1 are an interesting approach; however, adverse effects were found when anti-ICAM-1 antibodies were used in a phase III clinical study with ischemic stroke patients." (PMID 23372835, 2013).
ischemic stroke (continued). "Moreover, it abolished the inhibitory effect of 0.7 g/kg/day ethanol on ICAM-1 and E-selectin expression under physiological conditions and following ischemic stroke." (PMID 39682755, 2024). "However, the inhibitory effect of ethanol on both ICAM-1 and E-selectin under physiological conditions and following ischemic stroke was diminished in Tie2CreERT2/+/L-PGDSfl/fl mice." (PMID 39682755, 2024). "And ICAM-1 might be related to post ischemic stroke thrombosis since a recent study has suggested the involvement of ICAM-1 in coagulation." (PMID 37342100, 2023). "There is still no explanation for the association between ICAM-1 and neurological deterioration following an ischemic stroke." (PMID 37342100, 2023). "After ischemic stroke, the expression of intercellular adhesion molecule-1 (ICAM-1), vascular cell adhesion molecule 1 (VCAM1), integrin, and E-selectin is increased, which promotes peripheral immune cell penetration into the brain tissue and aggravates nervous system inflammation." (PMID 37458258, 2023). "However, a relationship of periphery ICAM-1 levels with the levels of inflammation in CNS in ischemic stroke remains to be established." (PMID 37342100, 2023). "Our results showed that ischemic stroke increased the frequency of ICAM-1+, E-selectin+, and VCAM-1+ CD31+ brain endothelial cells in the ipsilateral hemisphere of vehicle-treated MCAO mice compared to that of sham controls and the contralateral hemisphere of vehicle-treated MCAO mice." (PMID 35860274, 2022). "The results of marker discovery studies on plasma of ischemic patients presented markers, such as BNP, von Willebrand factor, ICAM-1, CRP, and interleukin-6, through biomarker research progress associated with causes of ischemic stroke, which differed from the biomarkers identified in our study." (PMID 32466277, 2020). "Thus, inhibition of ICAM-1 after ischemic stroke prevents leukocyte adhesion and benefits BBB function recovery." (PMID 31447648, 2019). "The authors state that the combination of decreased ICAM-1 expression and decreased cell permeability may have the potential to be useful in the clinical treatment of ischemic stroke." (PMID 31024058, 2019). "In addition, immunoreactivity of the adhesion molecules ICAM-1 and P-selectin were significantly more increased after ischemic stroke in infected brains as compared to mock." (PMID 31043599, 2019). "Circulating ICAM-1 levels are significantly increased following ischemic stroke in patients." (PMID 30524357, 2018). "Previous clinical trials, with a murine IgG2a anti-ICAM-1 antibody, targeting another ICAM-1 epitope than BI-505, enlimomab, have been performed, with the aim of reducing detrimental inflammatory activity in ischemic stroke, rheumatoid arthritis and burn injuries." (PMID 28158311, 2017). "Previous studies indicate NRG-1 reduces the expression of ICAM-1 following ischemic stroke." (PMID 24433482, 2014). "NF-κB and ICAM-1 are essential to elicit ischemia-induced blood–brain barrier damage; thus, the CaCCs inhibition could have a beneficial effect in the treatment of ischemic stroke." (PMID 38791133, 2024). "Moreover, leukocytes (especially regulatory T lymphocytes) have significant function in thromboinflammation during ischemic stroke by promoting ICAM-1 expression on platelets and endothelia which facilitates adhesion of granulocytes and platelets to the vessel wall." (PMID 32908630, 2020). "Therefore, we concluded that TMEM16A inhibition could alleviate the disruption of BBB permeability after ischemic stroke by reducing ICAM-1 expression and neutrophil accumulation." (PMID 31447648, 2019). "Therefore, single nucleotide polymorphisms (SNPs) of the ICAM‐1 gene may strongly influence the expression and biological activity of ICAM‐1 and play a potentially important role in the pathogenesis of ischemic stroke." (PMID 31157518, 2019).
ischemic stroke (continued). "Furthermore, serum of ischemic stroke patients contains soluble ICAM-1, but not ICAM-2 in addition to being a risk factor." (PMID 31191232, 2019). "Therefore, ICAM‐1 is an important factor in thrombosis and may play an important role in ischemic stroke." (PMID 31157518, 2019). "Published studies have paid little attention to the correlations between Lp-PLA2 activity (or mass) and other ischemic stroke biomarkers, including CRP, MMPs, IL-6, TNF-α, VCAM1, ICAM1, S100B, vWF, BNGF, and MCP1." (PMID 36313479, 2022). "In this study, we found that 4-EG treatment repressed the expression of ICAM-1, VCAM-1, and E-selectin in brain endothelial cells, and diminished Evans blue leakage in ischemic stroke." (PMID 35860274, 2022). "ICAM-1, VCAM-1, and E-selectin mRNA levels were significantly attenuated in Poldip2+/− animals following ischemic stroke compared to sham controls." (PMID 33692398, 2021). "Adhesion molecules, such as ICAM-1, VCAM-1, and E-selectin, are increased in endothelial cells as a consequence of ischemic stroke and can be released into the blood." (PMID 32595585, 2020). "The levels of VEGF-A, ICAM-1, and VCAM-1 levels increased acutely (<8 h) in the blood of ischemic stroke patients compared to healthy controls, with VEGF-A and VCAM-1 levels also increased at 72 h." (PMID 32595585, 2020). "The endothelial cell adhesion molecules ICAM-1 and VCAM-1 are important for mediation of tissue injury during ischemic stroke." (PMID 32019570, 2020). "ICAM-1 inhibition was translated to the clinic through testing of the murine ICAM-1 antibody, Enlimomab in ischemic stroke." (PMID 31191232, 2019). "Our pre-clinical studies also found that ischemic stroke and TBI in mice significantly increase serum and heart ICAM-1 and MCP-1 expression as well as induce heart deficits." (PMID 30524357, 2018). "Our report shows that SLI treatment prevent brain injury after ischemic stroke by decreasing the expression of RAGE, MMP9 and inflammatory factors (COX-2, TNF-α and ICAM-1) in T1DM + MCAO rats." (PMID 28486941, 2017). "E-selectin not only stimulates ECs to express ICAM-1 but also EPCs to secrete IL-8, leading to enhanced homing and incorporation of EPCs to ECs capillary formation; the issue of whether this process occurs after ischemic stroke remains to be distinctly elucidated." (PMID 25888494, 2015). "In a rat ischemic stroke model, it inhibited the stimulation of microglia and astrocytes and decreased the expression of TNF-α, IL-1β, ıntercellular adhesion molecule (ICAM)-1, vascular cell adhesion molecule (VCAM)-1, inducible NO synthase (iNOS), and aquaporin-427." (PMID 40498951, 2025). "Previous research indicated that SalA may protect against peripheral immune cell infiltration after ischemic stroke by inhibition of the CD11b/CD18 complex, intercellular adhesion molecule-1 (ICAM-1), soluble epoxide hydrolase (sEH), and granulocyte adherence." (PMID 39139557, 2024). "ICAM-1 plays a direct role in the pathophysiology of ischemic stroke, infarct sizes are smaller in experimental models lacking ICAM-1 or treated with antibodies against it." (PMID 36745280, 2023). "Studies have shown that the adhesion molecules, such as E‐selectin, P‐selectin, ICAM‐1, and VCAM-1, are upregulated on the surface of brain endothelial cells within hours after ischemic stroke that promotes the influx of inflammatory cells into the ischemic brain." (PMID 35860274, 2022). "Transendothelial migration of PMN is mediated by adhesion molecules, e.g., of intercellular adhesion molecule 1 (ICAM-1) and platelet endothelial cell adhesion molecule-1 (PECAM-1), which exhibit an increased expression after induction of experimental ischemic stroke." (PMID 35087539, 2021). "The SNP of ICAM‐1 gene may strongly influence the expression and biological activity of ICAM‐1, and has a potentially important role in the pathogenesis of ischemic stroke." (PMID 31157518, 2019).